RN7SKP56 (RN7SK pseudogene 56)
Gene: Miscellaneous RNA gene on chromosome 6 (125,875,168 to 125,875,498, forward strand). Ensembl gene ENSG00000222445.
Homologues: Orthologues: chimpanzee 7SK (89% identical), mouse Gm55204 (53% identical). Paralogues in human: RN7SKP225 (63% identical), RN7SKP180 (63% identical), RN7SKP203 (63% identical), RN7SKP294 (63% identical), RN7SKP177 (62% identical), RN7SKP208 (62% identical), RN7SKP79 (62% identical), RN7SKP124 (62% identical), RN7SKP3 (62% identical), RN7SKP163 (61% identical), 7SK (61% identical), RN7SKP165 (61% identical), and 284 more.